Y_RNA (Y RNA )
Gene: Miscellaneous RNA gene on chromosome 6 (31,663,288 to 31,663,401, forward strand). Ensembl gene ENSG00000201207.
Homologues: Orthologues: chimpanzee Y_RNA (100% identical). Paralogues in human: Y_RNA (86% identical), RNY1 (85% identical), Y_RNA (84% identical), RNY1P11 (82% identical), Y_RNA (82% identical), Y_RNA (81% identical), RNY1P5 (80% identical), RNY1P7 (80% identical), Y_RNA (80% identical), RNY1P8 (79% identical), Y_RNA (79% identical), Y_RNA (78% identical), and 93 more.